DEFB107A (defensin beta 107A)
Description:
Has antibacterial activity.
Synonyms: BD-7; DEFB-7; DEFB107
Tractability: Antibody: UniProt places it where antibodies can reach, with medium confidence; UniProt predicts a signal peptide or a membrane-spanning region; its Gene Ontology location is reachable by antibodies, with medium confidence.
Gene: Protein-coding gene on chromosome 8 (7,811,720 to 7,815,716, reverse strand). Ensembl gene ENSG00000186572.
Subcellular location: Secreted
Pathways (Reactome):
Immune System: Beta defensins; Defensins
Gene Ontology:
Molecular function: lipid binding
Biological process: defense response to Gram-negative bacterium; defense response to Gram-positive bacterium; innate immune response
Cellular component: extracellular region
Homologues: Orthologues: chimpanzee DEFB107A (96% identical), dog CBD107 (63% identical), rat Defb13 (49% identical), mouse Defb13 (46% identical). Paralogues in human: DEFB107B (100% identical).